TAC1 (tachykinin precursor 1)
Diseases named in the same sentence as TAC1 in open-access papers (continued):
Sharing a sentence is not in itself a finding about the gene and the disease.
bacterial sepsis (1 paper, 2011). "Bacterial LPS has also been shown to upregulate the expression of TAC1 and deletion of the TAC1 gene in mice reduces the effects of bacterial sepsis and LPS induced organ damage." (PMID 21294877, 2011).
Moyamoya disease (1 paper, 2025). Moyamoya disease (MMD) is a rare intracranial arteriopathy involving progressive stenosis of the cerebral vasculature located at the base of the brain causing transient ischemic attacks or strokes. "RGS1, MUC1, KCNA2, TAC1, and SOST were all found to be up-regulated in moyamoya disease." (PMID 40462179, 2025).
oesophageal cancer (1 paper, 2018). "This was supported by a study of TAC1 hypermethylation in oesophageal cancer which found that ~13% of their cohort had the biomarker present in plasma but not in the matched tumor tissue." (PMID 30087854, 2018).
pemphigus vulgaris (1 paper, 2021). Pemphigus is a group of chronic autoimmune skin diseases characterized by blister formations on the outer layer of the skin and the mucous membranes. "TAC1 (substance P gene) was enriched in human pemphigus vulgaris compared to generalized pemphigus foliaceous, and this was also a DEG in our canine dataset." (PMID 34660634, 2021).
rhabdoid tumor (1 paper, 2021). An aggressive malignant embryonal neoplasm usually occurring during childhood. "Overall survival of rhabdoid tumor patients with low expression (n = 20) of TACR1 or TAC1 was compared to the patients with high expression (n = 19) based on the median of TAC1 or TACR1 expression." (PMID 35049682, 2021). "Next, we made use of the pediatric rhabdoid tumor study from The cBio Cancer Genomics Portal to understand in detail whether TACR1 or TAC1 expression in rhabdoid tumors correlates with biological or clinical characteristics." (PMID 35049682, 2021). "In this study, we present for the first time the expression of TACR1 and TAC1 in rhabdoid tumors." (PMID 35049682, 2021). "For the first time, we present the expression of TACR1 and TAC1 in rhabdoid tumors, the potent inhibitory effect of the NK1R antagonist aprepitant in this tumor entity and the analysis of apoptotic pathways of rhabdoid tumor cells upon treatment with aprepitant." (PMID 35049682, 2021).
Telangiectasia (1 paper, 2023). Telangiectasias refer to small dilated blood vessels located near the surface of the skin or mucous membranes, measuring between 0.5 and 1 millimeter in diameter. "Significant expression changes existed also for genes responsible for the pathogenesis of telangiectasia (upregulation of Sst, Sstr1, Sstr2, Tac1, Tacr1, Svbp), and for general growth (Sst, Sstr1, Sstr2)." (PMID 37830614, 2023).
tumor (92 papers, 1991 to 2026). "Analyzing the methylation of circulating tumor DNA (ctDNA), such as dynamic monitoring of SOX17 and TAC1, correlates with tumor burden and provides a non-invasive tracking option." (PMID 40725119, 2025). "In patients with comorbidities, the ANG-1, VEGF, PF-4, and TAC-1 genes clustered more closely in tumor tissue than in platelets (37.4% and 15.8% of the variance of PC1 and PC2)." (PMID 37176055, 2023). "SST hypermethylation, with subsequent decrease in gene expression, has been observed in 81% of HNSCC samples and has been linked to tumor extent, disease stage, galanin type 2 receptor (GALR2) methylation, and tachykinin-1 (TAC1) methylation." (PMID 36769317, 2023). "SSTR1 hypermethylation has been detected in 64% of HNSCC samples and has also been associated with tumor extent, disease stage, SST hypermethylation, and increased expression of galanin (GAL), GALR2, TAC1, and tachykinin type 1 receptor (TACR1)." (PMID 36769317, 2023). "In patients without comorbidities, an increase in the expression of ANG-1 and LAMPTB4 was observed, while the expression of TAC-1 was decreased in tumor tissue compared to platelets." (PMID 37176055, 2023). "Precisely, GSE micro array data shows tendencies towards a decreasing expression of total TACR1 with tumor stage progression, while TAC1 tends to increase with higher stages." (PMID 34070805, 2021). "Data mining in publicly available datasets, such as TCGA, GEO, and CCLE, with additional consideration of OncoLnc survival data, allowed for linkage of differential expression of TACR1 and TAC1 to tumor progression and EMT state of cancer cells." (PMID 34070805, 2021). "Varying expression of TACR1-tr and TAC1 release is in line with the TCGA data, where we found trends related to tumor stages." (PMID 34070805, 2021). "We next explored the mRNA expression of several neuropeptides, including Calca, as well as Calcb and Tac1, which are considered to be coexpressed with Calca, in different tumor types according to the TCGA database." (PMID 34800986, 2021). "Upregulating LOC134466 and TAC1, and 5-Aza treatment sucessfully arrested tumour progression in both in vitro and in vivo studies." (PMID 30485833, 2018). "It was interesting to find molecules such as TAC1 that were overexpressed in the tumor samples, although they were not overexpressed in the tumor, indicating that this was possibly associated with the tumor microenvironment rather than the tumor cells." (PMID 37176055, 2023). "Although NK-1R antagonists may be therapeutic in inhibiting CCA tumor growth, current studies are limited and expression levels of TAC1 and NK-1R in human CCA tumor tissues and correlation with metastases or survival rates are still undefined." (PMID 32069926, 2020). "Moreover,we found that both LOC134466 and its target gene TAC1 was hypermethylated in EC tumor tissues." (PMID 30485833, 2018). "Consistently, LOC134466 and TAC1 were hypermethylated and downregulated in all tumor cell lines." (PMID 30485833, 2018). "It was found that both LOC134466 and TAC1 were dramatically silenced in tumor tissues, indicating that methylation of gene might negatively affect gene expression." (PMID 30485833, 2018). "Besides, the function of LOC134466 and TAC1 in EC was further confirmed by Tumor Xenograft." (PMID 30485833, 2018). "Finally, our data may suggest that at a genomic level small intestinal NETs may be distinguished by at least two distinct, secretory subtypes, serotonin-producing neoplasms and serotonin/substance P (TAC1/tachykinin)-producing lesions." (PMID 25023465, 2014). "The more distinct white stripe emerged in tumor group indicated that both LOC134466 and TAC1 were hypermethylated in EC." (PMID 30485833, 2018). "This study concluded that hypermethylation of TAC1 and SEPT9 promoter regions was detectable earlier in patients postresection compared to CEA and was a better predictor of tumour recurrence." (PMID 29038612, 2017).
tumor (continued). "The methylation statuses of the promoters of 11 tumor-related genes (p16, RASSF1A, E-cadherin, H-cadherin, MGMT, DAPK, DCC, COL1A2, TAC1, SST, and GALR1) were analyzed in 133 HNSCC cases using quantitative methylation-specific PCR." (PMID 27027429, 2016). "SSTR1 hypermethylation in 64% of cases was correlated with tumor size (P = 0.037), stage (P = 0.037), SST methylation (P < 0.001), and expression of galanin (P = 0.03), GALR2 (P = 0.014), TAC1 (P = 0.023), and tachykinin receptor type 1 (TACR1) (P = 0.003)." (PMID 25734919, 2015). "SSTR1 methylation was significantly correlated with tumor size, stage, and methylation of galanin, GALR2, TAC1, TAC1R, H-cadherin, MGMT, DAPK, and DCC methylation." (PMID 26251921, 2015). "SST methylation in 81% of HNSCC tumor specimens significantly correlated with tumor size (P = 0.043), stage (P = 0.008), galanin receptor type 2 (GALR2) methylation (P = 0.041), and tachykinin-1 (TAC1) (P = 0.040)." (PMID 25734919, 2015). "Methylation of SST was associated with several clinicopathologic factors, including tumor size (P = 0.043), stage (P = 0.008), GALR2 methylation (P = 0.041), TAC1 methylation (P = 0.040), and DAPK methylation (P = 0.012) (Table 1and S1 Table)." (PMID 25734919, 2015). "Methylation of SST was significantly related to several clinicopathologic factors, including tumor size, stage, DAPK methylation, TAC1 methylation, and GALR2 methylation." (PMID 26251921, 2015). "Overall, we observed that TACR1 and TAC1 were expressed across different tumor stages and independent of gender or age of diagnosis." (PMID 35049682, 2021). "Of the tumor cell lines, G-401 showed the highest expression of TAC1, while HepG2 cells have no detectable expression of TAC1 in mRNA levels." (PMID 35049682, 2021). "Surprisingly, the analysis of TAC1 expression revealed that the RT of the kidney (T190) had the highest expression, whereas the other tumor tissue samples showed almost no expression." (PMID 35049682, 2021). "Furthermore, three-gene combinations detected even the smallest lung nodules, with the combination of CDO1, SOX17, and HOXA7 having the overall best performance, while the combination of CDO1, TAC1, and SOX17 was best in tumor sizes less than 1.0 cm." (PMID 32138766, 2020). "Interestingly, while the combination of CDO1, SOX17, and HOXA7 showed the overall best performance in our patient cohort, the combination of CDO1, TAC1, and SOX17 had the best performance in the subgroup with tumor size less than 1.0 cm." (PMID 32138766, 2020). "Consistent with RNA-seq data, the expression of SLN, TAC1, MYH8, and PGAM2 were down-regulated, whereas SDRC7, KRT16, S100A9, IL36G, and FABP9 were up-regulated in both blood (Animal #9, #11, and #12) and skin (Animal #6, #7, and #8)-induced tumours relative to normal skin controls." (PMID 31340720, 2019). "Therefore, the detection of methylation in the genes SST, TAC1, SEPT9, and HLTF may enable early detection and assist in more effective intervention during postresection tumour recurrence compared to conventional markers." (PMID 29038612, 2017).
cancer (78 papers, 1999 to 2025). A tumor composed of atypical neoplastic, often pleomorphic cells that invade other tissues. "Higher serum methylation levels of TAC1 6 months postoperation and an increasement of methylation levels during the first half-year interval were shown to be associated with cancer recurrence (both P ≤ 0.001)." (PMID 30944663, 2019). "Serum methylated SST was significantly associated with cancer-specific survival among all other detected markers tested in the same study (TAC1, MAL, SEPT9, NELL1, CRABP1, EYA4, and CEA) at the preoperative time point, while its methylation status after operation had no value on prognosis." (PMID 30944663, 2019). "Information on this gene has just begun as itsinvolvement in cancer biology could be linked to the NK receptor gene family as well as the Tac1 gene." (PMID 19277104, 2008). "The Tac1 gene, which is linked to breast and other cancers, couldbe suppressed by translational inhibition." (PMID 19277104, 2008). "The involvement of the neurokinin-1 receptor (NK1R; TACR1)/substance P (SP; TAC1) complex in cancer has been described previously." (PMID 35049682, 2021). "An in silico analysis by us also revealed the possible involvement of the Tachykinin 1 (Tac1) gene, a gene for SP, in cancer." (PMID 34692834, 2021). "The TAC1 expression has been reported in several types of cancer." (PMID 37176055, 2023). "The combination of serum methylated TAC1, SEPT9, and NELL1 could also depict a higher cancer-specific death risk after CRC surgical resection (P = 0.001) than any single marker at 6 months but not after 1 year postsurgery." (PMID 30944663, 2019). "Thus, Tac1 appears to be central to cancer remission, and also during low tumor burden at an early period, and perhaps prior to clinical detection." (PMID 18575622, 2008). "However, whether the LOC134466 / hsa-miR-196a-5p / TAC1 axis we built exists in other kinds of cancers and how it plays roles respectively need to be further explored." (PMID 30485833, 2018). "As expected, significantly more methylated epialleles of SOX17, CDO1, TAC1, and HOXA7 were detected in cancer patients compared to the benign group." (PMID 37039321, 2023). "Consistent with DNA methylation profiles in plasma, methylation of CDO1, TAC1, SOX17, and HOXA7 were detected more frequently in patients with cancer compared with controls." (PMID 32138766, 2020). "The methylation detection rate of CDO1, TAC1, SOX17, and HOXA7 were significantly higher in cancer group than in the benign group (p < 0.001)." (PMID 32138766, 2020). "The promoter hypermethylation of CDO1, TAC1, HOXA7, and SOX17 were detected more frequently in the plasma of cancer patients compared with controls." (PMID 32138766, 2020). "In the present study, higher methylation frequencies of CDO1, TAC1, HOXA7, and SOX17were also observed in the plasma of cancer patients." (PMID 32138766, 2020). "Tac1 appears to regulate this interaction by regulating theexpressions of SDF-1α and CXCR4 on both the cancer cells and mesenchymal stemcells." (PMID 19277104, 2008). "This population might be responsible for cancer resurgence and could also begin to device translational studies with combinations of available CXCR4 and Tac1 peptide receptor antagonists." (PMID 18575622, 2008).
infection (25 papers, 2005 to 2025). The state of being infected such as from the introduction of a foreign agent such as serum, vaccine, antigenic substance or organism. "Substance P exerts additional control over the immune response during infection, with Tac1-deficient mice exhibiting a clear reduction in the expression of select chemokines that result in neutrophil and T-cell recruitment." (PMID 40501768, 2025). "Although the expression of Ccl2 increased in WT and Tac1−/− mice infected with C. rodentium, this was not statistically significant across genotypes suggesting that select chemokines are modulated by infection and deficiency in Tac1." (PMID 40501768, 2025). "In IAV infected QX-314 administered mice, we observed a significant increase in the expression of genes encoding the neuropeptides CGRP (Calca) and Substance P (Tac1) at both days 4 and 8 post infection compared to IAV vehicle mice." (PMID 38626267, 2024). "Consistent with these reductions in Tac1−/− mice, infection-induced colonic histopathology was significantly attenuated relative to infected WT mice." (PMID 40501768, 2025). "Infection with C. rodentium resulted in significantly reduced fecal bacterial shedding and the number of colonic adherent bacteria in Tac1−/− mice compared to WT controls 10 days post-infection (dpi)." (PMID 40501768, 2025). "In assessing the innate and adaptive immune responses during infection, significant reductions in TNFα and select chemokines that aid recruitment of neutrophils and T-cells were observed in Tac1−/− mice compared to WT." (PMID 40501768, 2025). "Infection of Tac1−/− mice with C. rodentium significantly reduced bacterial burden and fecal shedding compared to WT mice." (PMID 40501768, 2025). "Although C. rodentium infection significantly increased expression of the proinflammatory cytokine Tnfa in WT mice, this was significantly reduced in Tac1−/− mice 10 days post-infection." (PMID 40501768, 2025). "Isolates Gu5 and DSY296 were recovered from later infection episodes of the same patients as isolates Gu4 and DSY294, respectively, but had acquired GOF mutations in TAC1 that caused CDR1/2 overexpression and fluconazole resistance." (PMID 38860767, 2024). "The expression of two genes (TAC1 and IL17A), which play major roles in inflammatory reactions, was remarkably up-regulated during the infection period." (PMID 24392094, 2014). "In addition, the expression of many sensory nerve markers, including Tac1 and TRPV1, and the lung fiber innervation patterns themselves are plastic and can be modulated by inflammation and infection." (PMID 35365503, 2022).
inflammation (22 papers, 2007 to 2023). Aberrant reaction of the microcirculation characterized by movement of fluid and leukocytes from the blood into extravascular tissues. "Splice variants of TAC1 also generate neurokinin A and neuropeptide K. The role of SP in pain pathways and neurogenic inflammation has been well established, including effects of vasodilatation and plasma extravasation." (PMID 25690155, 2015). "Thus, gaining a better understanding of the mechanisms controlling the activity of TAC1prom has been a continuing priority since the discovery of the involvement of the TAC1 gene in neurogenic inflammation." (PMID 21294877, 2011).
neurological disorders (5 papers, 2016 to 2024). "The mRNAs of Rgs9, Gpr88, Drd2, Sh3rf2, Tac1, Serpina 9, Rxrg, Drd1, Rasgrp2, Six3, Gpr6, Pdyn, Gng7, and Pde1b were all upregulated (p < 0.05); all of these have been reported to be more or less related to nervous system diseases." (PMID 33819195, 2021).
adenocarcinoma (1 paper, 2024). A common cancer characterized by the presence of malignant glandular cells. "SOX17, TAC1, CDO1, HOXA9 and ZFP42 were the 5 genes that were identified in the Cancer Genome Atlas (TCGA) with highly prevalent DNA methylation in lung squamous and adenocarcinoma, but not in normal lung tissue." (PMID 38315228, 2024).
neurodevelopmental disorder (1 paper, 2013). A behavioral and cognitive disorder with onset during the developmental period that involves impaired or aberrant development of intellectual, motor, or social functions. "TAC1 is expressed in brain throughout development, and the brain is the primary tissue affected in neurodevelopmental disorders." (PMID 23759142, 2013).
TAC1 also shares sentences with these, for which no sentence is quoted: migraine (99 papers); fibromyalgia (20); Headache (20); psoriasis (20); glioblastoma (19); diabetes (14); tendinopathy (14); Alzheimer disease (12); angioedema (11); atopic dermatitis (11); COVID-19 (10); acne (9); aspiration pneumonia (9); heart failure (9); acute pancreatitis (8); pneumonia (8); rosacea (8); cystitis (7); Hyperglycemia (7); neuropathic pain (7); allergic rhinitis (6); magnesium deficiency (6); melanoma (6); urticaria (6); allergic disease (5); apical periodontitis (5); colorectal cancer (5); Constipation (5); injury (5); peripheral neuropathy (5).
A further 285 diseases each share a sentence with TAC1 in 5 papers or fewer.